TLR4 (toll like receptor 4)
Diseases named in the same sentence as TLR4 in open-access papers (continued):
Sharing a sentence is not in itself a finding about the gene and the disease.
infection (continued). "Enhanced TNF production in response to LPS after infection with an infectious agent unrelated to bacteria might result from enhanced TLR4 expression, although such an increased TLR4 expression was at best modest after LDV infection." (PMID 37240201, 2023). "During infection or injury, degradation of high-molecular weight HA (HMW-HA) to low-molecular weight HA (LMW-HA) by host hyaluronidases and reactive oxygen species (ROS) is thought to stimulate proinflammatory responses mediated by TLR2 and TLR4 signaling." (PMID 37747229, 2023). "Increased mCD14 and sCD14 levels result in the delivery of LPS to TLR4 after infection with gram-negative bacteria, which further affects the secretion of CCL2 and enhances the migration of immune cells." (PMID 37445719, 2023). "In order to investigate whether the activation of TLRs other than TLR4 also increases GLP-1 secretion, we used a polymicrobial infection model through cecal ligation puncture (CLP) in wild-type and TLR4-deficient mice." (PMID 36982420, 2023). "Although an in vitro study indicated that SEA attenuates IFN-γ-induced MHC class II expression is partly through interaction between SEA and TLR4, the mechanism of decreased MHC molecule expression in the advanced infection group remains unclear." (PMID 37817226, 2023). "The employed docking server illustrated significant binding of the constructed multiepitope vaccine at both TLR isotypes, TLR4 and TLR2, where these innate immunity receptors are highly reported for their important role within the host’s defense throughout infections by K. pneumonia." (PMID 36911530, 2023). "Even though TLR-4 is essential for causing antileishmanial activity in macrophages during experimental L. donovani infection, in our work, we did not detect any discernible differences in TLR-4 expression between LdWT and LdCen−/− infection." (PMID 37111420, 2023). "TLR4 is part of the Toll-like receptor family and gives origin to the intracellular signaling cascade that leads to the pro-inflammatory process and to the production of PGE2 following an infection." (PMID 37511267, 2023). "For instance, infection of mouse bone marrow-derived macrophages (BMDM) with H. pylori stimulates the production of interleukin-6 (IL-6) and IL-1β via TLR2, IL-12, and IL-10 through the TLR4 pathways." (PMID 36317079, 2022). "In regard to GLY mediated protection, in the current study, GLY was unable to reduce the levels of RAGE and HMGB1 in the absence of TLR9, but significantly reduced TLR4 levels in TLR9KO corneas after infection." (PMID 36422579, 2022). "To better understand the therapeutic mechanism of HSSD in H1N1-infected mice, we measured the expressions of TLR4/NF-κB p65 and HIF-1α/IL17 pathways according to the prediction of network pharmacology results in lung tissues on the day 5 post-infection by using RT-qPCR and IHC staining." (PMID 36386710, 2022). "Infections caused by Gram-negative bacteria induce IL27 production, and this cytokine interacts with monocytes increasing TLR4 expression and enhancing the LPS-induced inflammatory response." (PMID 35264251, 2022). "In the case of infection, LPS is extracted from bacterial membranes and bound to LPS binding protein (LBP), which transfers LPS through interaction with CD14 to toll-like receptor 4 (TLR4)." (PMID 35326484, 2022). "Toll-like receptor 4 (TLR4) is a pattern-recognition receptor (PRR) that can recognize lipopolysaccharides (LPS) and initiate the immune response, to protect the body from infection." (PMID 35281916, 2022). "Although the relative level of TLR4 mRNA was significantly down-regulated (p < 0.0001) in L26-treated cells compared with the ST infection, the TLR5 mRNA expression in L26-treated cells was without significance." (PMID 36556320, 2022).
infection (continued). "The ability of PMSS1 re-isolates to stimulate TLR4 was increased compared to the pre-infection strain, but the difference was not significant, presumably because the cag-T4SS of this wt strain also strongly contributes to the stimulation of NF-kB." (PMID 35176125, 2022). "The infection of C. perfringens increased the mRNA expressions of TLR-2, TLR-4 and NF-κB (P < 0.01) in jejunal mucosa, whereas the addition of EA in diets decreased the mRNA abundances of TLR-2, NF-κB (P < 0.01) and TLR-4 (P < 0.05)." (PMID 35436978, 2022). "Meanwhile, it perfectly compensates for the deficiency that only extracellular LPS can be detected by the Toll-like receptor 4 (TLR4)/myeloid differentiation-2 (MD-2) complex, thereby accomplishing the complete intracellular and extracellular clearance of LPS infection." (PMID 35693810, 2022). "The underlying mechanism of SEP was involved in the increased activity of TLR4/STAT3/CD64 signaling in macrophages, and provided some evidence for its potential clinical development as immunoprophylaxis or adjunct antimicrobial agents for infection." (PMID 35370674, 2022). "The specific binding of these potential ligands to TLR4/MD2 and their effect was examined using in a first step a set of cell-based assays and in a second step the more complex human-based immune responsive 3D-infection models." (PMID 35208698, 2022). "In the mouse infection model, the RSV F protein was reported to be an effector to trigger the production of IFN-β via interaction with TLR4; while in monocyte-derived dendritic cells (mDCs), the soluble G protein was demonstrated to inhibit TLR3/4-mediated IFN-β production." (PMID 35308390, 2022). "Our data therefore suggest that SARS‐CoV‐2 virus particles are not sensed by extracellular TLRs, including TLR4, but that infection via ACE2 is required." (PMID 35099061, 2022). "Female C57BL/6 (B6), TLR4 knockout (TLR4KO), myeloid specific TLR4KO (mTLR4KO), their wildtype (WT) littermates, and TLR9 knockout (TLR9KO) mice were infected with P. aeruginosa KEI 1025 and treated with GLY or PBS onto the cornea after infection." (PMID 36422579, 2022). "In addition, sequential infections in outbred SPexp mice resulted in an increased prevalence of TLR2- and TLR4-expressing leukocytes." (PMID 35878936, 2022). "Vaccine engagement of innate immunity via ligands to TLR2 or TLR4 or presentation via virus-like particles elicited robust, protective immunity in the absence of post-infection inflammatory responses including pulmonary eosinophilia." (PMID 36560488, 2022). "TLR4 plays a role in the progression of SARS-CoV-2 infection by activating the production of type I interferons and pro-inflammatory cytokines to fight the infection." (PMID 36366521, 2022). "Similarly, production of nitric oxide (NO) 24 h post-infection was also dependent on the presence of TLR2 and TLR4." (PMID 35899053, 2022). "However, in response to infection, marked differences were also observed in the CMP frequency of CD206, TLR4 and Ly-6C, all of which have important host defense functions." (PMID 35572576, 2022). "However, overexpressing Neu1 and silencing siglec-E together followed by infection was able to effectively upregulate both MyD88- and TRIF-dependent pathways of TLR4 activation." (PMID 33763070, 2021). "Surprisingly, they discovered TLR2 activation but not TLR4 stimulation in transfected HEK293 cells during infection with B. pseudomallei LPS." (PMID 34456925, 2021). "Therefore, MyD88 is required for protection from lethal infection of SARS-CoV-1, especially that it is a main adaptor protein for multiple TLRs, not only TLR4." (PMID 33505220, 2021). "After infection with RV- SA11, the expression of TLR4, MyD88, and NF-κB mRNA and protein increased significantly, which could be abolished by SBP treatment." (PMID 33897431, 2021).
infection (continued). "One study has described TLR2 activation in O. tsutsugamushi-infected mice and cultured HEK293 cells and others identified no role for TLR4 in mice during infection." (PMID 34320039, 2021). "Infection with Gram-negative bacteria, the release of LPS and activation of the TLR4/NF-κB signaling pathway are the principal factors responsible for the disease." (PMID 34573559, 2021). "Ad-TLR4 infection restored the expression of both TLR4 and SREBP1a whereas Ad-SREBP1a infection restored SREBP1a expression without altering TLR4 expression in the LKO livers." (PMID 33816466, 2021). "Ascending high dose infection induced TLR-4 activation, a ligand for LPS (Gram negative [E. coli] cell wall component) and activated proinflammatory transcription factor P-NF-κB expression." (PMID 34855804, 2021). "Thus, the infection/inflammation-modified expression of HMGB1, RAGE, and TLR4 showed a therapeutic potential of these biomolecules." (PMID 34439812, 2021). "have shown that the expression of TLR2, TLR4 and MyD88 did not change in bovine macrophages after 6 h of infection with M. bovis in relation to the non-infected control." (PMID 34335572, 2021). "For example, TLR4-knockout mice infected with Japanese encephalitis virus (JEV) show reduced CNS inflammation, viral RNA, leukocyte infiltration, proinflammatory cytokine expression and, importantly, increased resistance to lethal infection." (PMID 33487119, 2021). "During an acute infection by FMDV, not only FMDV but also host proteins, such as TLR4, could inhibit IFN production and induce an inflammatory response, resulting in competition between the host and pathogen for survival." (PMID 34524915, 2021). "Similar to costimulatory and other surface expressed molecules, mRNA expression of TLR4 (10.7-fold) and TLR21 (15-fold) was upregulated in S. Typhimurium-treated chMoDCs at 6 h post-infection (P < 0.001) but reduced almost to a basal level at 24 h post-infection." (PMID 34446765, 2021). "This process is catalyzed by phospholipase A2 (PLA2) related enzymes and is induced by a variety of cell-activating signals, including stimulation of inflammation or infection of the tumor necrosis factor receptor (TNFR) and stimulation of Toll-like receptor 4 (TLR4)." (PMID 34769074, 2021). "However, agonist treatment together with Δrgg3 infection resulted in decreased TNF-α production in response to lipopolysaccharide (LPS; TLR4), heat-killed Listeria monocytogenes (HKLM; TLR2), and CpG oligodeoxynucleotide (ODN1826; TLR9)." (PMID 33947757, 2021). "No or minor dermal lesions appeared at the site of infection in WT, single mutant Tlr4-/-, Ifnar1-/-, or Ifngr1-/- C57BL/6J mice or CD-1 mice." (PMID 34423779, 2021). "Likewise, total and free LA levels were upregulated by Mtb or TLR2 and TLR4 stimulation, suggesting an enhanced uptake of this essential ω6 PUFA precursor by host macrophages upon infection." (PMID 34951591, 2021). "On one hand, a hypo-inflammatory response in the TLR-4 pathway is consistent with vulnerability to infection, particularly by gram negative bacteria." (PMID 34497610, 2021). "The results showed that SNPs rs109915208, rs110514940, and rs110905610 on SLC11A1, c.480G>A and c.625C>A on PGLYRP1, and c.2021C>T on TLR4 were monomorphic in both seropositive and seronegative cattle and therefore had no influence on the infection outcome." (PMID 33644146, 2021). "The principal factors responsible for the disease are infection with Gram-negative bacteria, the release of Lipopolysaccharides (LPS) and activation of the TLR4/NF-κB signaling pathway." (PMID 34573559, 2021). "In the case of TLR4 activation, upon lipopolysaccharide (LPS) binding, it bestows the early mounting of nonspecific immune response to infections." (PMID 33562108, 2021). "This site differs from the LPS binding site, making it possible to selectively inhibit HMGB1/TLR4 activation without compromising LPS/TLR4 binding and its protective effects after infection." (PMID 34684184, 2021).
infection (continued). "Previous studies have shown that there is increased TLR4 expression in the fetal membranes in spontaneous labor at both term and preterm regardless of infection, suggesting an important role of TLR4 in parturition." (PMID 32582166, 2020). "We performed initial experiments to establish the optimal dose for S. pneumoniae serotype 3 strain 1195 infection and the time required to mount an IIR, parameters that allowed us to study the myeloid cell subpopulations involved, as well as the role of TLR4 and MyD88 expression." (PMID 33042124, 2020). "Western blotting showed no change in TLR4 protein levels following infection of Vero cells with PEDV." (PMID 32340172, 2020). "LPS is a typical stimulus used to mimic infection in many animal studies of MIA; indeed, it induces a well-characterized inflammatory response by activating toll-like receptor 4 (TLR4) and a consequent increase in several pro-inflammatory factors, such as cytokines, and glia cells activation." (PMID 32906830, 2020). "Given that TLR4 can potently induce cell apoptosis, our finding provided evidence that C. coli LOS was involved in triggering the inflammatory scenario in the intestines upon infection." (PMID 33261211, 2020). "HEK-293-TLR4 cells demonstrated TLR4 signalling in response to infection with P. aeruginosa only (1–4 hours post infection, p<0.001), but no TLR4 signalling was observed after infection with P. histicola." (PMID 33031374, 2020). "Under conditions of infection with WT V. vulnificus, HT-29 cells upregulated KLF2, KLF4, and KLF6 and downregulated NLRP3, TLR4, and CXCR4, suggesting that the MARTX toxin interrupts inflammatory responses, NF-κB signaling, and mitogen-activated protein kinase (MAPK) signaling in infected cells." (PMID 32817457, 2020). "In our experiments using CRL2471 cells, infection of macrophages took place in the absence of specific antibodies and TLR4." (PMID 32462327, 2020). "Hence, upon peroral infection of hma IL10-/- mice, C. coli induced the secretion of pro-inflammatory cytokines not only in the intestinal tract, but also systemically, in a TLR4-dependent fashion." (PMID 32443576, 2020). "This study demonstrates that TLR2, TLR4, and DC-SIGN interactions on the DC surface could have important implications in the course of infections." (PMID 32722168, 2020). "However, therapeutic targeting of either TLR2 or TLR4 from day two post-infection provided significant protection, suggesting that both TLR2 and TLR4 contribute to disease pathogenesis driven by damage-associated molecular patterns (DAMPs)." (PMID 32260457, 2020). "Hence, upon peroral infection of hma IL10-/- mice, C. coli induced clinical signs in a TLR4-dependent fashion." (PMID 32443576, 2020). "In contrast to our findings, TLR-2 and TLR-4 are not involved in phagocytosis and ROS production in C. albicans infection although these receptors are essential to control the infection in vivo." (PMID 33193308, 2020). "Therefore, secondary abiotic IL10-/-, and TLR4-/- IL10-/-, mice were subjected to peroral human FMT on three consecutive days, one week prior to infection." (PMID 32443576, 2020). "Prior to infection studies, we first confirmed that the synergistic effects of combined TLR4 and NOD2 stimulation were not affected by the entrapment of PRR agonists into PLGA nanoparticles." (PMID 32927915, 2020). "LPS recognition by TLR4 is universally attributed to triggering host defense responses against infection by Gram-negative bacteria, our data here indicated the decreased TLR4 expression in response to the oprC-deficient mutation of P. aeruginosa." (PMID 32849593, 2020). "In contrast, the levels of TLR4 mRNA were comparable between klotho WT and KO mice, and were not altered in their lungs after the infection." (PMID 33329595, 2020). "However, the mRNA levels for TLR4, tnf alpha, akr1, and TLR2 remained unchanged or increased after vaccination but decreased after infection." (PMID 32344637, 2020).
infection (continued). "A marked increase in the TLR4 expression was observed after BDL and LPS infection." (PMID 31942020, 2020). "For clusters and heterozygosity models, infection status was not influenced by any parameter except a negative association with elevation in TLR1LA, TLR3, TLR4 as top model." (PMID 33209285, 2020). "Then we compared the expressions of RLRs and TLRs after infection, and found that the expressions of MDA5 were much higher than RIG-I, while the expressions of TLR3 was much higher than those of TLR2 and TLR4." (PMID 31947624, 2020). "Following infection of differentiated THP-1 cells with Bt at an MOI of 1, treatment with TLR4-ab–compared to an isotype control–significantly reduced supernatant TNF-α concentrations in the presence of rhLTF (p = 0.03) or phLTF (p = 0.008), but not media alone." (PMID 32764765, 2020). "Our work shows that without TLR4, mice are unable to restrict the proliferation of the pbgA-lpxC salmonellae and generally succumb to these infections." (PMID 31611279, 2019). "Common polymorphisms in genes encoding key innate immune pattern recognition receptors including TLR2, TLR4, TLR9, CD14, and NOD2 have been associated with the development of infections in some but not all studies." (PMID 30873165, 2019). "While infection of CNSΔTLR4 animals did not demonstrate a difference in clinical disease compared to WT animals, disruption of TLR4 specifically within microglia, lead to worsened paralysis." (PMID 31309928, 2019). "Because we observed that intermediate monocytes express more TLR2 and TLR4 than classical and non-classical monocytes after infection with leishmania, we analyzed the frequency of cells expressing TNF and IL-10 on monocyte subsets expressing TLR2 and TLR4." (PMID 31119102, 2019). "In our study, gp43 stimulated PMNs to produce IL-17A only after blocking TLR4, suggesting that gp43 might take advantage of the TLR4/TLR2 interactions during IL-17 production to control inflammatory reactions during an active infection." (PMID 31886295, 2019). "The infection with L.braziliensis increased the expression of TLR2 and TLR4 on monocytes from HS." (PMID 31119102, 2019). "Three days post-infection, the E. coli challenge significantly increased the expression of nuclear factor-κB (NF-κB), peroxisome proliferator-activated receptor-γ (PPAR-γ), toll-like receptor 4 (TLR4), IL-1β, and IL-6 (P < 0.05) and tended to increase the expression of TNF-α (P = 0.052)." (PMID 29948799, 2019). "Reduced TACE activity was shown to promote endotoxin tolerance without engagement of TLR4, which circumvents an overwhelming inflammation upon infection." (PMID 30897723, 2019). "Thus, not only do TLR4 and TLR2 mRNA and protein increase in the myometrium at term, but TLR4 null mutant mice are resistant to infection-induced PTB18,19." (PMID 30886179, 2019). "TLR4 anergy can occur in HEU infants without necessarily translating to increased vulnerability to infection." (PMID 29491865, 2018). "For instance, infection of rats with Hymenolepis diminuta increased expression of TLR2 and TLR4 in the jejunum and colon, and H. polygyrus infection in mice induced TLR4 expression in lamina propria T cells." (PMID 29867790, 2018). "In contrast, using anti-TLR2 or TLR4 neutralizing antibodies, we did not observe any modulation of the inflammatory response of human keratinocytes during wild-type strain infection." (PMID 30070169, 2018). "An OmpA-deficient strain of K. pneumoniae shows increased stimulatory activities in airway cell responses through activation of TLR2-, TLR4-, and NOD1-mediated recognition; accordingly, this mutant is completely excluded from the lung in an animal infection model." (PMID 30153274, 2018). "During an infection with Gram-negative bacteria, as a ligand for TLR4, S100A8 is strongly induced in endotoxic shock." (PMID 29942307, 2018).